NELL1 (neural EGFL like 1)
Description:
Plays a role in the control of cell growth and differentiation. Promotes osteoblast cell differentiation and terminal mineralization.
Synonyms: IDH3GL; FLJ45906
Tractability: Antibody: UniProt places it where antibodies can reach, with medium confidence; UniProt predicts a signal peptide or a membrane-spanning region; its Gene Ontology location is reachable by antibodies, with medium confidence. PROTAC: ubiquitination databases record sites on it.
Gene: Protein-coding gene on chromosome 11 (20,669,551 to 21,577,711, forward strand). Ensembl gene ENSG00000165973.
Subcellular location: Cytoplasm; Nucleus envelope; Secreted
Gene Ontology:
Molecular function: protein binding; heparin binding; protein kinase C binding; calcium ion binding
Biological process: negative regulation of osteoblast proliferation; negative regulation of protein catabolic process; positive regulation of bone mineralization; positive regulation of osteoblast differentiation; regulation of gene expression; nervous system development; positive regulation of ossification; regulation of osteoblast differentiation
Cellular component: cytoplasm; non-collagenous component of basement membrane; nuclear envelope; perinuclear region of cytoplasm; extracellular region
Genetic constraint (gnomAD): Loss-of-function variants: 60 observed, 90.01 expected, observed/expected ratio (o/e) 0.67, 90% interval 0.54 to 0.83. The upper end of that interval is the gene's LOEUF score, 0.83, which puts it in group 3 of 6, group 1 being the genes least tolerant of losing a copy. Missense variants: 859 observed, 895.37 expected, observed/expected ratio (o/e) 0.96, 90% interval 0.91 to 1.01. Synonymous variants: 304 observed, 311.51 expected, observed/expected ratio (o/e) 0.98, 90% interval 0.89 to 1.07.
Homologues: Orthologues: chimpanzee NELL1 (99% identical), macaque NELL1 (99% identical), pig NELL1 (96% identical), rabbit NELL1 (95% identical), mouse Nell1 (93% identical), dog NELL1 (93% identical), rat Nell1 (93% identical), tropical clawed frog nell1 (73% identical), guinea pig NELL1 (61% identical), zebrafish nell3 (15% identical). Paralogues in human: NELL2 (55% identical).
Diseases named in the same sentence as NELL1 in open-access papers:
NELL1 is named in the same sentence as 68 diseases in open-access papers, as found by Europe PMC text mining. Sharing a sentence is not in itself a finding about the gene and the disease. The quoted sentences say what the papers report.
craniosynostosis (17 papers, 2011 to 2026). Craniosynostosis is defined as the premature fusion of one or more cranial sutures leading to secondary distortion of skull shape resulting in skull deformities with a variable presentation. "Nel-like type 1 (NELL1) is located on sheep chromosome 21 (20804714~21839088 bp), and is a novel growth factor associated with craniosynostosis with high specificity for bone and chondrocyte lines." (PMID 36952432, 2023). "Neural epidermal growth factor-like 1 protein (Nell-1) is first studied because of its association with human craniosynostosis (CS)." (PMID 33072736, 2020). "Neural epidermal growth factor-like 1 protein (Nell-1) is first studied because of its association with human craniosynostosis." (PMID 33072736, 2020). "NELL-1 is a novel secreted protein associated with premature fusion of cranial sutures in craniosynostosis that has been found to promote osteoblast cell differentiation and mineralization." (PMID 21931789, 2011). "Through promoter analyses, we have recently identified a new direct transcriptional target of Runx2, Nell-1, a craniosynostosis (CS)–associated molecule with potent osteogenic properties." (PMID 20939017, 2011). "Moreover, RUNX2 is also responsible for regulating expression of genes that, when deregulated, cause craniosynostosis like NEL-like 1 (NELL1)." (PMID 34946295, 2021). "Researchers have found, for the first time, that NELL-1 expression is increased in cranial intramembranous bone from patients with craniosynostosis." (PMID 39255297, 2024). "NEL-like molecule-1 (NELL1), a new secretory protein originally identified in unilateral coronal craniosynostosis in humans, plays an important role in osteogenic differentiation, bone regeneration, chondrogenesis and inflammation." (PMID 35651940, 2022). "The upregulation of NELL-1 causes congenital cranial defects attributed to the premature fusion of sutures; mice with transgenic overexpression of NELL-1 also develop craniosynostosis." (PMID 33808418, 2021). "Nearly two decades ago, Nell-1 was first observed to be upregulated in prematurely fusing and fused sutural sites of craniosynostosis (CS) patients, suggesting Nell-1’s involvement in osteochondral development." (PMID 29316655, 2018). "The expression of Nell‐1 is tightly regulated by Runx2, a vital mechanistic convergence point for the development of craniosynostosis." (PMID 28470873, 2017). "Nel‐like molecule‐1 (Nell‐1) is a secreted protein first identified through its overexpression in pathologically fusing and fused suture specimens from patients with craniosynostosis." (PMID 28470873, 2017). "Nell‐1 was initially detected at fusing and fused sutures from craniosynostosis patients." (PMID 28470873, 2017). "Overexpression of NELL-1 results in craniosynostosis in humans and mice, whereas lack of Nell-1 expression is associated with skeletal undermineralization." (PMID 26082355, 2015). "For example, in 1999, Ting's group first identified the osteogenic activity of another secretory protein, neural EGFL like 1 (NELL1), in active bone formation sites of human craniosynostosis patients." (PMID 34766140, 2021). "A transgenic model of human craniosynostosis (CS) showed that the upregulation of Nell‐1 expression is the cause of UCS and that the development of craniofacial cartilage and bone cannot continue without Nell-1." (PMID 36175952, 2022). "Thus, it is conceivable that this up‐regulation of Nell‐1 may be resulted from the BMP9‐induced up‐regulation of Runx2, suggesting that BMP9 may play a potential role in regulating the patency of cranial sutures and the development of craniosynostosis." (PMID 28470873, 2017).
membranous nephropathy (17 papers, 2021 to 2025). "Other novel proteins including neural epidermal growth factor-like 1 protein (NELL-1) and Semaphorin 3B have recently been identified to be associated with membranous nephropathy." (PMID 33413188, 2021). "NELL1 is a target antigen in malignancy-associated membranous nephropathy." (PMID 34332599, 2021). "By employing laser capture microdissection of glomeruli, newer antigens have been identified in nephrotoxin-induced membranous nephropathy and include neural epidermal growth factor-like 1 (NELL1) and proprotein convertase subtilisin/kexin type 6 (PCSK6)." (PMID 41441614, 2025). "This study aimed to comprehensively characterize the clinical and pathological features, treatment strategies, and outcomes of patients with neural epidermal growth factor-like 1 protein (NELL-1)-positive membranous nephropathy (MN)." (PMID 40978725, 2025). "Neural epidermal growth factor-like 1 protein (NELL1) is the second most common target antigen in membranous glomerulonephritis (MGN)." (PMID 39249508, 2025). "Neural epidermal growth factor-like 1 (NELL1) membranous nephropathy (MN) is notable for its segmental deposit distribution, IgG1 dominant deposits, and comparatively high rate of spontaneous remission." (PMID 38596642, 2024). "Furthermore, multiple recent studies have also shown the importance of NELL1 in inflammatory bowel disease and membranous nephropathy, amongst other diseases." (PMID 35447734, 2022). "For example, chronic exposure to NSAIDs has been associated with secondary membranous nephropathy, which can present as the nephrotic syndrome associated with the PCSK6 antigen, while penicillamine and mercury exposure have been linked to antibodies against NELL1." (PMID 41441614, 2025). "This case series identified 23 patients with NELL-1 (+), PLA2R (−), and THSD7A (−) membranous nephropathy (MN) from a cohort of 531 non-SLE MN patients." (PMID 40978725, 2025). "Not all patients were tested for THSD7A-, NELL1-, or EXT1/2-related antibodies; otherwise, this would have affected the generalizability of the results (other antibody-related membranous nephropathy)." (PMID 41041325, 2025).
autoimmune disease (8 papers, 2022 to 2025). A disorder resulting from loss of function or tissue destruction of an organ or multiple organs, arising from humoral or cellular immune responses of the individual to their own tissue constituents. "The two cases of NELL1-associated MN observed in our cohort do not show any associated disease, consistent with the evidence that NELL1-associated MN is the second most common form of MN, accounting for approximately 10% of cases after the exclusion of autoimmune diseases." (PMID 40612566, 2025). "Notably, MN associated with EXT1/EXT2 and NELL1-related malignant tumors may be linked to autoimmune diseases, such as systemic lupus erythematosus and mixed connective tissue disease." (PMID 40852718, 2025). "A variety of clinical settings have been linked to NELL1-associated PMN, which includes cancer, drugs, infections, autoimmune diseases, stem cell transplantation, and de novo MN following kidney transplantation." (PMID 38707806, 2024). "Two loci are genome-wide significant, one of which is the well-known MHC locus, with the other being an association to the NELL1 gene on chromosome 11, a locus that has not been observed in previous case/control GWAS for T1D or other autoimmune diseases." (PMID 36817429, 2023). "Most NELL-1-positive MN patients do not have autoimmune diseases, but NELL-1 positivity is associated with a higher incidence of tumors." (PMID 36003509, 2022). "It was found that most exostosin-positive patients are complicated by systemic lupus erythematosus or other autoimmune diseases, so NELL-1 might be a target antigen of secondary membranous nephropathy, but the mechanisms underlying podocyte injury are not clear." (PMID 36003509, 2022). "For example, nephrologists appear to adopt a more aggressive malignancy workup for the antigens associated with malignancy, NELL1 and THSD7A, but not for EXT1/2 which has been associated with autoimmune diseases." (PMID 40500560, 2025).
osteoporosis (6 papers, 2015 to 2026). A condition of reduced bone mass, with decreased cortical thickness and a decrease in the number and size of the trabeculae of cancellous bone (but normal chemical composition), resulting in increased fracture incidence. "Altogether, these findings suggest that NELL-1 deficiency plays a role in osteoporosis and demonstrate the potential utility of NELL-1 as a combination anabolic/antiosteoclastic therapeutic for bone loss." (PMID 26082355, 2015). "Here we explore the causative and therapeutic possibilities of manipulating NELL-1 signalling in osteoporosis." (PMID 26082355, 2015). "However, a recent genome-wide study of single-nucleotide polymorphisms found a linkage between NELL-1 and osteoporosis in human patients." (PMID 26082355, 2015). "Several investigations have consistently shown that NELL-1 plays a crucial role in the osteogenic differentiation of osteoblasts, and it has been found to interact synergistically with other genes implicated in the development of osteoporosis, such as Bone Morphogenetic Protein 2 (BMP2)." (PMID 39255297, 2024). "While preclinical data were encouraging, clinical studies correlating serum Nell-1 levels with osteoporosis remain scarce." (PMID 41626054, 2026). "NELL-1 has been identified as a promising therapeutic target for treating osteoporosis in animal studies." (PMID 39255297, 2024). "Here we show that Nell-1-haploinsufficient mice have normal skeletal development but undergo age-related osteoporosis, characterized by a reduction in osteoblast:osteoclast (OB:OC) ratio and increased bone fragility." (PMID 26082355, 2015). "In sum, the present study describes a new role for NELL-1 as an aetiological factor and a treatment of osteoporosis." (PMID 26082355, 2015). "Considering that BMPs are crucial genes for bone and cartilage development, leveraging the synergistic effect of these genes with NELL-1 could hold significant promise in the treatment of osteoporosis." (PMID 39255297, 2024). "NELL-1 loss-of-function studies demonstrated protective function against osteoporosis as Nell-1 haploinsufficient mice with reduced endogenous NELL-1 developed reduced bone mineral density (BMD), reduced osteoblast activity, increased osteoclast activity, and increased bone fragility with age34." (PMID 37723136, 2023). "The growth factor NELL-1 induces bone formation during development, but its role in osteoporosis is unknown." (PMID 26082355, 2015). "In contrast, by 18 months of life the Nell-1+/6R mouse developed significant osteoporosis." (PMID 26082355, 2015). "Finally, we have found that NELL-1 has potential dual uses as both a local bone-forming growth factor as well as a systemic osteogenic factor for osteoporosis." (PMID 26082355, 2015). "Given that NELL-1 is primarily expressed in osteoblasts, targeting this gene for therapeutic interventions could hold promise for treating bone-related conditions such as TBS and osteoporosis." (PMID 39255297, 2024). "Despite the well-demonstrated osteogenic effects of NELL-1 (refs 24, 25, 26, 27), there has been little understanding of the signalling pathway through which the effects of NELL-1 are exerted, nor the potential role of NELL-1 in osteoporosis." (PMID 26082355, 2015).
osteosarcoma (4 papers, 2011 to 2024). A usually aggressive malignant bone-forming mesenchymal neoplasm, predominantly affecting adolescents and young adults. "Cntnap4 exerts its effects partly via interaction with NELL-1, an osteosarcoma associated protein, and subsequent positive regulation of MAPK intracellular components." (PMID 36599925, 2023). "An investigation on human osteogenic sarcoma and primary human osteoblast cells the findings indicate that Osterix functions as a direct transcriptional regulator, suppressing NELL-1 gene expression." (PMID 39255297, 2024). "Recently, we reported that the secreted glycoprotein NELL-1 modulates osteosarcoma (OS) disease progression in part via altering the sarcomatous extracellular matrix (ECM) and cell-ECM interactions." (PMID 36599925, 2023). "We conclude that NELL1/CNTNAP4 activates ERK/MAPK signaling, and this is a feature of an aggressive phenotype in osteosarcoma." (PMID 36599925, 2023). "Further correlation analysis found BNIP3 to have a significantly positive correlation with MYC, NELL1, SAR1A, PLOD2, and other genes proven to promote osteosarcoma metastasis." (PMID 37190333, 2023).
colon cancer (3 papers, 2015 to 2021). "Both STAC2 and NELL1 promoter CpG island hypermethylation has been reported in metastatic breast cancer and primary colon cancer, respectively and GRP is implicated in the development of tumorigenicity and drug resistance." (PMID 34922619, 2021). "As a gene encoding a secreted protein regulating skeletal ossification, NELL1 has also been proposed to be a tumor suppressor gene in colon cancers." (PMID 31531345, 2019). "The Nell-1 gene has been mapped to chromosome 11p15; the high prevalence of Nell-1 promoter methylation in colon cancer suggests a role for inactivation of the gene in colon tumorigenesis." (PMID 26090379, 2015).
glioma (3 papers, 2011 to 2021). A benign or malignant brain and spinal cord tumor that arises from glial cells (astrocytes, oligodendrocytes, ependymal cells). "A study showed that there were binding sites between Nell-1 and Osterix, and Osterix acted as a negative regulator of Nell-1 in Saos-2, U2OS, HeLa and Glioma cells." (PMID 33072736, 2020). "In addition to the Saos2 cells, the transcriptional repression of Nell-1 promoter by Osterix was also detected in other human cell lines including an immature osteoblast, U2OS cells and two non-osteoblastic cell lines, Hela and Glioma cells." (PMID 21931789, 2011).
Idiopathic membranous nephropathy (3 papers, 2021 to 2024). "Currently, several specific antigens, M-type receptor for secretory phospholipase A2(PLA2R1), thrombospondin type-1 domain-containing 7A(THSD7A), and neural epidermal growth factor-like 1 protein (NELL-1), are discovered associated with the onset of idiopathic membranous nephropathy (IMN)." (PMID 34703677, 2021).
sarcoidosis (3 papers, 2024 to 2025). Sarcoidosis is a multisystemic disorder of unknown cause characterized by the formation of immune granulomas in involved organs. "A recent study showed that PLA2R (38.9%) and neural epidermal growth factor-like-1 protein (NELL-1) (22.2%) positivity are common in sarcoidosis patients with MN." (PMID 39734346, 2024). "While the exact mechanism remains unknown, it was speculated that increased inflammation in sarcoidosis might cause increased glomerular expression of PLA2R and NELL-1 which might trigger antibody-mediated MN development." (PMID 39734346, 2024). "Interestingly, results for recent studies identified NELL1 in many secondary forms of MN (malignancies, drugs, sarcoidosis, hepatitis): these pieces of evidence clearly show how NELL1-associated MN overcomes the historical classification in primary and secondary MN." (PMID 40612566, 2025).
Arthritis (2 papers, 2022). Inflammation of a joint. "Among the polymorphisms found more frequently in AS patients with arthritis, JAK2 rs7857730, IL-23R rs11209008 and rs10489630, CYP1B1 rs1056836, NELL1 rs8176786, KL rs564481, MEFV rs224204, IL-2RB rs743777, and IL-1A rs1800587 have been described." (PMID 35629038, 2022).
autism spectrum disorder (2 papers, 2023 to 2024). A spectrum of developmental disorders that includes autism, and Asperger syndrome. "Nell-1-haploinsufficient (Nell-1+/6R) mice display core abnormalities similar to autism spectrum disorder." (PMID 39140105, 2024). "Interestingly, Nell-1+/6R mice demonstrated core autism spectrum disorder-like deficits, which could be corrected by Risperidone, an FDA-approved anti-autism, anti-bipolar medicine." (PMID 38102659, 2023).
gastric cancer (2 papers, 2015 to 2019). A primary or metastatic malignant neoplasm involving the stomach. "Using matrix-assisted laser desorption/ionization time-of-flight MS and MassCLEAVE reagent, we compared Nell-1 hypermethylation levels among tumor tissues, paracarcinoma tissues, and normal tissues from gastric cancer patients." (PMID 26090379, 2015). "Our results show that Nell-1 promoter hypermethylation is a common event in gastric cancer." (PMID 26090379, 2015). "Based on these findings, we hypothesized that Nell-1 is inactivated via promoter hypermethylation in human gastric cancer and that this modification may be used as a biomarker for early detection of the disease." (PMID 26090379, 2015). "To assess whether Nell-1 is inactivated via promoter hypermethylation in human gastric cancer, we investigated the methylation status of the Nell-1 promoter in 75 samples from 25 patients using MALDI-TOF MS." (PMID 26090379, 2015). "This suggests that Nell-1 can be used as a biomarker for the diagnosis of gastric cancer." (PMID 26090379, 2015).
glomerular disease (2 papers, 2024 to 2025). "However, this survey identified that nephrologists have limited access to testing and exposure to antigens other than PLA2R, THSD7A, NELL1, and EXT1/2 even amongst glomerular disease experts." (PMID 40500560, 2025).
inflammatory bowel disease (2 papers, 2022 to 2024). A spectrum of small and large bowel inflammatory diseases of unknown etiology. "NELL1 was also found to directly or indirectly act as an important biomarker for many diseases, such as osteoporosis, metabolic diseases, neuro-related diseases including bipolar or depression, inflammatory bowel disease, and tumor or tumor-related membranous nephropathy." (PMID 35447734, 2022).